INS (insulin)
Diseases named in the same sentence as INS in open-access papers (continued):
Sharing a sentence is not in itself a finding about the gene and the disease.
diabetes (continued). "Diabetes mellitus (DM) is a metabolic disorder characterized by chronic hyperglycemia resulting from defects in insulin secretion and action." (PMID 39439490, 2024). "Additionally, reduced insulin sensitivity has been reported in Asians compared to non-Asians, potentially increasing the likelihood of poor diabetes control and complication risk." (PMID 39027768, 2024). "Diabetes mellitus (DM) is a chronic metabolic disorder characterized by impaired insulin secretion or activity in peripheral tissues, resulting in persistent hyperglycemia." (PMID 39852560, 2024). "In this cohort, none of the participants reported persistent hypoglycemia that has been observed in a small fraction of these patients after diabetes remission, but rather mild self-limited hypoglycemia that might reflect abnormal regulation of insulin secretion." (PMID 40302951, 2024). "We were unable to investigate the association of the family history with insulin secretory capacity or TIR since we could not determine the presence or absence of a family history of diabetes." (PMID 38839813, 2024). "Diabetes Mellitus (DM) is a chronic condition characterized by either enough production of insulin or stop completely the production of insulin secretion by the pancreas." (PMID 38594267, 2024). "Therefore, the primary goal of the OMED2 (Optimization of Medication in Elderly with Diabetes) study is to investigate the effect of promoting the deprescribing of insulin/sulphonylureas in general practice on T2D-complications in older patients (≥ 70 years) who are overtreated." (PMID 39049109, 2024). "Based on changes in GAD antibody titers and all negativity for anti-insulinoma-associated antigen-2 (IA-2), insulin, and zinc transporter 8 (ZnT8) antibodies, the patient was diagnosed with type 2 diabetes mellitus rather than slowly progressive type 1 diabetes mellitus (SPIDDM)." (PMID 39247010, 2024). "Diabetes mellitus (DM) is a widespread metabolic disease with a rapidly growing global population; it is characterized by chronic hyperglycemia resulting from inadequate insulin secretion and/or insulin action and is attributable to the interactions between genetic and environmental factors." (PMID 38903985, 2024). "Despite numerous hypotheses and potential pathologic mechanisms proposed for cognitive impairment in diabetes - ranging from vascular disease, hypoglycemic events, direct insulin effects on the brain, oxidative stress, to advanced glycation end products - the exact pathways remain unclear." (PMID 39583396, 2024). "Diabetes mellitus (DM) is a metabolic disorder characterized by elevated blood glucose levels (hyperglycemia) resulting from either insufficient insulin production (Type 1) or impaired insulin sensitivity (Type 2)." (PMID 39056672, 2024). "Finally, although the overall frequency of hypoglycaemia was within the usual frequency for children with diabetes on insulin, our education team counsels patients on how to treat hypoglycaemia, and all patients are provided with glucose tablets and gluco-gel to treat hypoglycaemia." (PMID 39035710, 2024). "Two major types of diabetes mellitus are type 1 diabetes mellitus, which is caused by pancreatic beta cell destruction, and type 2 diabetes mellitus, which primarily occurs due to insulin resistance whereby our body does not effectively respond to insulin." (PMID 39795285, 2024). "Diabetes is particularly suited to the approach of stem cell therapies for a variety of conditions, as transplantation of the stem-cell-based insulin-producing pancreatic β-cells or glucose-responsive islet-like organoids could potentially provide long-lasting therapy or even a cure." (PMID 39280004, 2024). "Finally, naturalistic experiment designs seek to relate neuroimaging-based metabolic measures to modulations of circulating insulin levels that were caused not by the experimenter, but by the participant, via self-administration of insulin for diabetes treatment." (PMID 37611907, 2024).
diabetes (continued). "Diabetes mellitus (DM) is a chronic metabolic disorder characterized by high levels of blood glucose due to insufficient insulin production or impaired insulin action." (PMID 38351959, 2024). "Under normal conditions, IGF-I is more potent than insulin; however, in the plasma of obese patients, IGF-I was positively associated with body fat mass, while low IGF-I has been linked to obesity-related complications such as insulin resistance and type 2 diabetes mellitus." (PMID 38612666, 2024). "However, HOMA-IR is less accurate as an indicator of insulin resistance in patients with diabetes mellitus with high fasting plasma glucose (FPG) levels (who may have a decreased insulin secretion)." (PMID 38905235, 2024). "In addition, the authors looked at the efficacy of berberine 1.5 g/day given to 48 diabetics with inadequately controlled glucose levels for three months, in addition to standard hypoglycemic drugs, such metformin, acarbose, sulfonylureas, or insulin." (PMID 39796448, 2024). "Sustained HIF-1 overexpression in β-cells by the deletion of the Vhl gene (encoding the von Hippel–Lindau protein) causes impaired insulin secretion and glucose intolerance in mice, indicating that the upregulation of HIF-1α is deleterious to β-cell function and contributes to diabetes." (PMID 38673770, 2024). "In early pregnancy, lipids increase, thereby raising blood levels of free fatty acids, which may impair insulin sensitivity and create a vicious circle between high lipid levels and IR, leading to impaired glucose tolerance and the development of diabetes mellitus." (PMID 39075387, 2024). "Enhanced tissue insulin sensitivity may also have a positive impact on diabetes progression." (PMID 39408213, 2024). "Therefore, inflammatory mediators may affect the homeostasis of glucose and mediate the occurrence and development of diabetes by inhibiting insulin secretion and affecting insulin sensitivity." (PMID 38617433, 2024). "Similarly, a prospective, parallel-assignment, open-label, phase III study examined changes in MMSE scores following 12-week liraglutide treatment in individuals with diabetes (glycated hemoglobin [HbA1c] > 7.0% and on oral antidiabetic drugs or insulin for at least 3 months)." (PMID 39501255, 2024). "However, the crossover sub-study in healthy controls comparing the effect of the two infusion rates resulted in comparable results, suggesting that a two-fold difference in insulin infusion rate cannot explain differences between the two diabetes groups in this study." (PMID 38376580, 2024). "Interestingly, diabetic patients on metformin therapy have a reduced risk of lung cancer, while insulin-treated diabetic women have a 27% increased risk of developing lung cancer compared to those not treated for diabetes." (PMID 39044884, 2024). "IR is characterized as a state of decreased responsiveness of insulin-targeting tissues to high physiological insulin levels and is considered the pathogenic driver of numerous cardiovascular diseases, nonalcoholic fatty liver disease (NAFLD), and type 2 diabetes mellitus (T2DM)." (PMID 39212734, 2024). "Beta-cells within the pancreas harbor PD-1; with the upregulation of T-cells with the use of PD-1 inhibitors, it is postulated that beta-cells may react maladaptively to the elevated autoreactive T-cells leading to its failure to produce insulin resulting in diabetes." (PMID 38606021, 2024). "Icodec is a novel recombinant insulin that has been developed to have an analogue of human insulin with distinct pharmacokinetic (PK) and pharmacodynamic (PD) properties, enabling its use for weekly (instead of daily) administrations in patients affected by diabetes mellitus." (PMID 38610878, 2024). "Diabetes mellitus (DM) is a metabolic disease with hyperglycemia, which is attributed to the defect of insulin secretion or the impairment of its biological function." (PMID 38204892, 2024).
diabetes (continued). "This was further confirmed by a prospective MESA study (n = 6814), which concluded that a CAC score of 0, regardless of the length of diabetes, use of insulin, or glycemic management, is linked to a lower risk of CVD, underscoring the role of CAC as an independent risk predictor." (PMID 39518317, 2024). "In line with our study, existing evidence also shows that combined aerobic exercise and IF improves metabolic parameters, such as decreased body weight and fat mass, enhanced insulin sensitivity (which could prevent diabetes, aging, and age-related disease), and increased cardiorespiratory fitness." (PMID 38786985, 2024). "Type 2 diabetes mellitus (T2DM) is a very common metabolic disorder characterized by the coexistence of two defects: pancreatic β-cell inability to secrete enough insulin and failure of insulin-sensitive tissues to compensate for this deficient insulin secretion properly." (PMID 39458076, 2024). "Diabetes mellitus (DM) represents a complex disease marked by elevated glucose levels and an increased basal metabolic rate because of a defect in insulin signaling." (PMID 38474769, 2024). "Type 2 diabetes mellitus (DM) arises from an imbalance between insulin sensitivity and insulin secretion." (PMID 38630691, 2024). "According to the definition provided by the World Health Organization (WHO), diabetes mellitus (DM) is a metabolic disorder characterized by untreated hyperglycemia resulting from inadequate insulin secretion and/or insulin resistance." (PMID 38275711, 2024). "In this observational study, we aimed to identify correlations between serum levels of HGF and EGF, insulin, glucagon, glucose, and primary serum lipids in patients with type 2 diabetes mellitus (DM), taking into account the impact of gender." (PMID 38654922, 2024). "Moreover, TD+ had higher FPG and daily insulin doses, which suggested that depression might play a significant role in adherence to diabetes care and result in poor glycemic control." (PMID 38599848, 2024). "It is well-established that obesity is a major risk factor for type 2 diabetes mellitus (T2DM), as excess adipose tissue promotes insulin resistance through increased secretion of inflammatory cytokines, free fatty acids, and other metabolic byproducts that disrupt insulin signaling." (PMID 39744011, 2024). "In both types of diabetes,β-cell dysfunction in insulin production, secretion, or exocytosisis a precursor, particularly in T2D.6,7 Despite manyinvestigations and findings, the exact mechanisms of T2D remain unknown,and effective drugs have not been sufficiently developed." (PMID 39713028, 2024). "Besides its role in diabetes, insulin increases cancer risk by promoting the proliferation of normal, preneoplastic, and neoplastic cells." (PMID 39339668, 2024). "Our findings suggest that, similarly to human diabetes, ectopic lipid deposition in the liver and skeletal muscle, impaired incretin signaling in the pancreas, and dysfunctional hepatic insulin signaling may together contribute to insulin resistance and the development of diabetes in cats." (PMID 39684905, 2024). "It highlights the importance of monitoring for new-onset diabetes and diabetic ketoacidosis, whether immunotherapy is active or discontinued, and ensuring comprehensive care including hospitalization, insulin management, and diabetes education if diabetic ketoacidosis is diagnosed." (PMID 39726058, 2024). "Diabetes mellitus (DM) is a disease characterized by high blood sugar levels due to pancreatic dysfunction, leading to reduced insulin secretion, abnormal insulin action, or a combination of both." (PMID 38998501, 2024). "Consequently, patients and caregivers exploring the latest in diabetes management are likely to discover extensive resources advocating for the benefits of insulin pumps and CGM systems, potentially leading to a decrease in attention toward transplantation options." (PMID 38666804, 2024).
diabetes (continued). "Moreover, COVID-19 patients with diabetes may face increased risks of acute metabolic complications, and require higher insulin doses." (PMID 39144619, 2024). "This activating STAT3 variant results in the decrease of insulin expression by repressing the transcriptional activity of ISL1, which could be involved in the pathogenesis of pancreatic β‐cell dysfunction and early‐onset diabetes." (PMID 38404237, 2024). "Therefore, another possible explanation for the association between PSM levels and CVD death lies in the dysfunction of ß-cells and insulin sensitivity and inflammation, which are pivotal patterns in the development of diabetes-related vascular complications, such as atherosclerosis." (PMID 38245731, 2024). "Diabetes mellitus (DM) is a metabolic disorder arising from limited insulin secretion or action during carbohydrate, fat, and protein metabolism, resulting in a rise in blood sugar levels (hyperglycemia)." (PMID 39507059, 2024). "Diabetes mellitus (DM) is characterized by hyperglycemia resulting from insulin resistance, inadequate insulin secretion, or excessive glucagon secretion." (PMID 38255714, 2024). "Finally, control of diabetes also requires initiation of insulin for many patients." (PMID 38708754, 2024). "Diabetes mellitus is caused by a lack of insulin secretion, which is known as type I diabetes." (PMID 39165448, 2024). "It is commonly employed in diabetes mellitus (DM) research because it has a specific affinity for pancreatic β-cells, resulting in a reduction in blood insulin levels and the development of hyperglycemia, effectively replicating the pathology of DM." (PMID 38929670, 2024). "Moreover, LDs in pancreatic islets accumulate in cases of nutritional stress, diabetes and dysfunction of β cells, suggesting that impaired LD production and degradation might be involved in impaired insulin secretion." (PMID 38642584, 2024). "Diabetes Mellitus (DM) is a chronic metabolic disorder characterized by elevated blood glucose levels due to the body's inability to produce insulin, effectively utilize it, or both." (PMID 39429548, 2024). "Dysregulation of insulin excretion and transportation into the CNS, despite a lack of insulin or resistance to the CNS, has extensively been noted in association with the elderly, obesity, diabetes, and several mental diseases, as well as appetite/satiety imbalances related to eating disorders." (PMID 38921683, 2024). "Diabetes mellitus (DM) is a chronic endocrine disorder characterized by dysregulation of blood glucose and insulin in the blood." (PMID 38892018, 2024). "The inverse relationship between the use of an insulin secretagogue or insulin and age of death firstly found in this study suggests that the careful monitoring and prevention of life-threatening hypoglycemia are crucial for extending healthy life expectancy in individuals with diabetes." (PMID 38592103, 2024). "Inthe diabetic disease state where insulin signaling is impaired, control of GLUT1expression by mTOR signaling shown here may connect impaired phagocyte GLUT1expression to worse S. aureus infection outcomes in diabetes." (PMID 38767353, 2024). "Hyperglycemia (high blood sugar) and inadequate insulin synthesis characterize a chronic metabolic condition known as diabetes mellitus (DM)." (PMID 39159188, 2024). "During the UKPDS (UK Prospective Diabetes Study) era, we learned that the natural history of T2D involved a progressive and irreversible deterioration of β-cell function leading to its complete exhaustion and the subsequent need for intensive insulin treatment." (PMID 38942960, 2024). "Diabetes mellitus (DM) is a chronic metabolic disease characterized by impaired insulin secretion and function." (PMID 38567310, 2024).
diabetes (continued). "For women of reproductive years living with type 2 diabetes, the relative merits of using non-insulin pharmacotherapies vs diabetes technology (dipeptidyl peptidase-4 inhibitors, glucagon-like peptide-1 receptor agonists and sodium−glucose cotransporter 2 inhibitors) are unknown." (PMID 38967667, 2024). "External carbohydrates cause fluctuations in blood glucose in patients with type 1 diabetes mellitus (DM); in this context, a ketogenic diet can reduce episodes of hypoglycemia and hyperglycemia along with insulin requirements." (PMID 39420895, 2024). "Diabetes mellitus (DM) is a chronic disease characterized by hyperglycemia resulting from insufficient insulin action and/or secretion." (PMID 38910705, 2024). "It demonstrates that smart insulin pen systems support MDI therapy patients in daily dosing decisions and may facilitate communication with the diabetes care team, which provides precision insulin management for all individuals on insulin therapy regardless of delivery method." (PMID 37855818, 2024). "Therefore, insulin may be considered as an option for improving diabetes control after the initiation of other therapies with established cardiovascular benefits in situations where optimum diabetes control has not been achieved previously." (PMID 39911238, 2024). "Diabetes mellitus (DM) is a chronic inflammatory condition characterized by increased insulin resistance and disrupted glucose regulation." (PMID 39403591, 2024). "Diabetes and its devastating effects on the cardiovascular system have both been greatly ameliorated by modern therapeutic advances, such as the ability to instantly regulate blood glucose levels (with inhaled insulin) and to do so for an extended period of time (with weekly injections)." (PMID 39211720, 2024). "During emerging adulthood, the probability of avoiding an insulin dose is greater, thus worsening the HbA1c values, which could explain the fact that 52.1% of our participants had an HbA1c above 53 mmol/mol, which is considered poor management of diabetes." (PMID 38999807, 2024). "Additionally, we also expect that an insulin pump could further help her with diabetes management, potentially reducing the recurrence of psychosis incidents." (PMID 38962606, 2024). "Diabetes mellitus (DM) is a chronic metabolic disorder characterized by persistent hyperglycemia, arising from defects in insulin secretion, insulin action, or a combination of both." (PMID 39712809, 2024). "Diabetes mellitus (DM) can be influenced by genetic or environmental factors and is often characterised by hyperglycaemia and insulin abnormalities." (PMID 39771098, 2024). "There is robust evidence that the use of diabetes technology such as continuous glucose monitoring and closed-loop insulin delivery can improve glycaemic management in outpatient settings; however, relatively little is known of its potential benefits and application in inpatient diabetes management." (PMID 38953925, 2024). "Associations with less frequent hypoglycaemia with insulin in our study is not explained by differences in diabetes duration since within trial duration was similar, reflecting the randomisation, and since our method of analysis is akin to summarising the within-trial associations across all trials." (PMID 38795153, 2024). "Diabetes mellitus is a chronic and metabolic disease, involving inappropriately increased blood glucose levels and systematic inflammatory responses accompanied by decreased insulin synthesis, insulin resistance (IR) or reduced metabolic response to insulin in many tissues." (PMID 38750544, 2024). "Additionally, CGA has been shown to improve insulin sensitivity by acting on the expression of enzymes and genes related to glucose metabolism, which may help mitigate the development of diabetes." (PMID 38921480, 2024).